PIKFYVE (phosphoinositide kinase, FYVE-type zinc finger containing)
Diseases named in the same sentence as PIKFYVE in open-access papers (continued):
Sharing a sentence is not in itself a finding about the gene and the disease.
melanoma (continued). "RNA sequence profiling suggested that PIKFYVE inhibitors upregulated an endoplasmic reticulum (ER) stress response involving interleukin‐24 (IL24; also known as MDA7) selectively in melanoma cells." (PMID 38414326, 2024). "Subsequent biochemical and genetic analyses revealed that PIKFYVE inhibitors induced a PERK‐dependent ER‐stress response that upregulated IL24 expression, which resulted in the termination of autophagy‐dependent melanoma cells in vivo as well as in vitro." (PMID 38414326, 2024). "Other alterations were found in genes reportedly altered in skin cancer, such as DGKI and SYK in melanoma or BCOR, PIKFYVE and NEDD4 in SCC." (PMID 28410231, 2017). "The combined effects of PIKFYVE inhibitors and ectopic expression of IL24 protein were additive, thereby confirming the therapeutic potential of elevating IL24 levels in the treatment of melanoma." (PMID 38414326, 2024). "PIKFYVE inhibitors disrupt lysosome homeostasis, which resulted in ER‐stress in melanoma cells and tumors but not in normal foreskin fibroblasts." (PMID 38414326, 2024). "Remarkably, a lack of PIP5K1C resulted in the sensitivity of melanoma, colorectal carcinoma, and osteosarcoma cell lines to PIKFYVE inhibitors." (PMID 38994949, 2024). "Inhibition of PIKFYVE activity induced IL24 expression with concomitant amplification of the PERK‐dependent ER‐stress response, which resulted in the termination of autophagy‐dependent melanoma cells in vivo as well as in vitro." (PMID 38414326, 2024). "RNA sequence profiling revealed that WX8 neither upregulated nor downregulated PIKFYVE RNA either in human melanoma A375 cells or in human foreskin fibroblasts HFF1." (PMID 36803256, 2023). "Thus, PIKFYVE inhibitors, either alone or in combination with other targeted drugs (including ectopic IL24 protein) exhibit significant therapeutic potential against PIKFYVE‐sensitive cancers, particularly melanoma that express high levels of endogenous IL24." (PMID 38414326, 2024). "Thus, PIKFYVE activity prevented over‐expression of IL24 in melanoma cells, whereas PIP4K2C did not." (PMID 38414326, 2024). "Nevertheless, analyses of melanoma, B-cell non-Hodgkin lymphoma and multiple myeloma cell lines reveal that a significant fraction (40% to 75%) are, on average, 14- to 26-fold more sensitive to PIKFYVE inhibitors than non-malignant cells." (PMID 38994949, 2024). "However, PIKFYVE RNA levels in cancer cells and normal cells remain unchanged in response to PIKFYVE inhibition, and PIKFYVE protein levels in melanoma cell lines vary only 3-fold, with no specific correlation between the resistant and sensitive cell lines." (PMID 38994949, 2024). "In our experiments, the PIKfyve inhibitor YM201636 and pyridinyl imidazole inhibitors SB202190 and SB590885 all promoted nuclear localization of TFEB, indicating that the drug-induced disruption of mTOR lysosomal tethering could inhibit mTORC1 activity in melanoma cells." (PMID 32531927, 2020).
breast cancer (5 papers, 2016 to 2023). A primary or metastatic malignant neoplasm involving the breast. "Downregulation of AKT1 in mechanistic experiments dephosphorylate PIKfyve on Ser and inactivate the PIKfyve site, resulting in mammary cancer metastasis through EGFR signaling pathways." (PMID 35341150, 2022). "Contrast with the report, our study suggested inhibition of PIKfyve activity promotes cell migration and invasion in breast cancer cells." (PMID 30445978, 2018). "Collectively, these data demonstrate that knockdown of Akt1 prolonged EGFR activation through inactivating PIKfyve in breast cancer cells." (PMID 30445978, 2018). "To investigate whether inhibition of PIKfyve is required for β-catenin nuclear accumulation via the prolonged activation of EGFR in breast cancer cells, we then treated MCF-7 and MDA-MB-231 cells with a PIKfyve specific inhibitor YM201636." (PMID 30445978, 2018). "Indeed, an increased EGFR co-localization with the early endosomes marker EEA.1 could be detected in MCF-7 and MDA-MB-231 cells treated with Akt1 siRNA, suggesting that PIKfyve activity was inhibited when Akt1 was knocked down in breast cancer cells." (PMID 30445978, 2018). "Therefore, we determined whether the increased phosphorylation levels of EGFR at Tyr1068 and EGFR total protein in Akt1 impaired breast cancer cells was due to the reduction in degradation through inactivating PIKfyve." (PMID 30445978, 2018). "We here disclose a novel Akt1/PIKfyve/EGFR/β-catenin signaling pathway, which contributes to the metastasis of breast cancer." (PMID 30445978, 2018). "Our results suggested that Flag-PIKfyve WT but not a S318A mutant PIKfyve binds to Akt1, confirming that Akt1 phosphorylates PIKfyve at Ser318 site in breast cancer cells." (PMID 30445978, 2018).
viral infection (5 papers, 2021 to 2024). "RMC-113 induces PIP4K2C-mediated autophagy and PIKfyve-mediated viral fusion, thereby simultaneously targeting two key pathways implicated in SARS-CoV-2 and other viral infections." (PMID 38659941, 2024). "Therefore, drug targeting PIKfyve to interfere with the endocytosis of host cells is an effective way to block virus infection." (PMID 37426619, 2023). "The study focused on the potential host targets of SARS-CoV-2, CD13, and PIKfyve, which may be involved in viral infection and the viral/cell membrane fusion stage of SARS-CoV-2 in humans." (PMID 37426619, 2023). "Furthermore, the PIKfyve inhibitor apilimod and autolysosome acidification blocker bafilomycin each successfully reduced viral infection to ~0.1% or 1% of vehicle-treated controls, respectively." (PMID 33723017, 2021).
B-cell non-Hodgkin lymphoma (4 papers, 2020 to 2025). The most common type of non-Hodgkin lymphoma. "Apilimod is a highly selective phosphatidylinositol 3-phosphate 5-kinase (PIKfyve) inhibitor and establishes robust cytotoxic effect against B-cell non-Hodgkin lymphoma." (PMID 36182930, 2022). "The cytotoxic effect of apilimod on B-cell non-Hodgkin lymphoma is mainly mediated by PIKfyve inhibition which disrupts endosomal and lysosomal homeostasis, thereby leading to cellular dysfunction and cancer cell growth arrest." (PMID 36182930, 2022). "Future studies should explore whether PIKfyve inhibition enhances anti‐CD20 efficacy across diverse B‐cell lymphoma subtypes, including diffuse large B‐cell lymphoma (DLBCL)." (PMID 40342289, 2025). "Our study identifies PIKfyve as a critical regulator of OBI‐induced LMP and DCD, providing mechanistic insights into how lysosomal integrity governs B‐cell lymphoma sensitivity to anti‐CD20 therapy." (PMID 40342289, 2025).
pancreatic cancer (4 papers, 2023 to 2025). "A study of human and mouse models of pancreatic cancer finds that inhibiting the lipid kinase PIKfyve interferes with the cancer’s lipid homeostasis, making it a potential target for drug development." (PMID 40269157, 2025). "We also found that PIKfyve inhibition improved anti-PD-1 efficacy against syngeneic pancreatic tumors established with orthotopic injection of KPC1361 cells, which translated into improved overall survival." (PMID 38011559, 2023). "This study identifies therapeutic targeting of PIKfyve as a strategy to upregulate surface expression of MHC-I in cancer cells and thus enhance response to immunotherapies across various cancer types, including those such as pancreatic cancer that are often unresponsive to immunotherapies." (PMID 38011559, 2023).
Alzheimer disease (3 papers, 2015 to 2016). A progressive, neurodegenerative disease characterized by loss of function and death of nerve cells in several areas of the brain leading to loss of cognitive function such as memory and language. "Here we show that the Amyloid Precursor Protein (APP), a central molecule in Alzheimer’s disease, associates with the PIKfyve complex (consisting of Vac14, PIKfyve and Fig4) and that the APP intracellular domain directly binds purified Vac14." (PMID 26216398, 2016). "Thus, an exogenous activator of the PIKfyve complex, expected to be beneficial in PIKfyve associated genetic diseases, may also be effective in Alzheimer's disease." (PMID 26934981, 2016). "If this model is correct then exogenous activation of the PIKfyve complex should mitigate or stop neurodegeneration in Alzheimer's disease." (PMID 26934981, 2016). "All three lines of evidence show that the AICD activates the PIKfyve complex in cells, a finding that is important for our understanding of the mechanism of neurodegeneration in Alzheimer's disease." (PMID 26934981, 2016). "Our work has shown that the central molecule in Alzheimer's disease, APP, binds to and activates the PIKfyve complex." (PMID 26934981, 2016). "Our recent work has shown that the intracellular domain of the amyloid precursor protein (APP), a molecule central to the aetiology of Alzheimer's disease binds to VAC14 and enhances PIKfyve function." (PMID 26934981, 2016). "In this study we demonstrate that the key player in Alzheimer's disease, APP, interacts with the PIKfyve complex and regulates the PIKfyve pathway in C. elegans, establishing an entirely novel role for APP." (PMID 26125944, 2015). "Given that inactivation of the PIKfyve complex leads to neurodegeneration and that APP plays a key role in Alzheimer's disease this finding prompted us to investigate this interaction in more detail." (PMID 26125944, 2015). "Our finding that APP regulates the PIKfyve complex in C. elegans in vivo hints at a novel molecular mechanism for neurodegeneration in Alzheimer's disease in which aberrant processing of APP by beta and gamma secretases would preclude APP from binding to and activating the PIKfyve complex." (PMID 26125944, 2015). "Finally, we show that PIKfyve activity is required for successful sorting of APP at endosomal membranes, establishing a complex and reciprocal relationship between APP and PIKfyve with interesting implications for our understanding of Alzheimer’s disease." (PMID 26216398, 2016). "However, our recent work has shown that the amyloid precursor protein (APP), a central molecule in Alzheimer's disease, binds to the VAC14 scaffold of the complex and enhances the activity of the PIKfyve complex in cells, providing a specific activator of this important enzyme complex." (PMID 26934981, 2016).
autoimmune disease (3 papers, 2017 to 2022). A disorder resulting from loss of function or tissue destruction of an organ or multiple organs, arising from humoral or cellular immune responses of the individual to their own tissue constituents. "Recently, a new potent and highly selective PIKfyve inhibitor has been characterized, shedding light on a new role for PIKfyve in inflammation and autoimmune diseases." (PMID 28396567, 2017). "An important enzyme involved in vesicle trafficking, phosphatidylinositol-3-phosphate 5-kinase type III (PIKfyve), has shown to be a promising in vitro therapeutic target for multiple diseases, including cancers, autoimmune diseases, and emerging viral diseases." (PMID 35962188, 2022).
bladder cancer (3 papers, 2011 to 2018). "PIKfyve dysfunction impairs endosome–Golgi transport, and a role for this pathway in nuclear transport is supported by the inhibition of ligand-stimulated EGFR trafficking to the nucleus in human bladder cancer cells in which PIKfyve function is impaired." (PMID 24295852, 2014).
cataract (3 papers, 2022 to 2023). Partial or complete opacity of the crystalline lens of one or both eyes that decreases visual acuity and eventually results in blindness. "Collectively, we identified PIKFYVE as a novel causative gene for congenital cataract and pinpointed the potential application of Baf-A1 for the treatment of congenital cataract caused by PIKFYVE deficiency." (PMID 35023829, 2022). "To further strengthen the correlation of PIKFYVE variants with cataracts, we screened another congenital cataract family, 10 sporadic cases with congenital cataract and 200 patients with age-related or complicated cataract." (PMID 35023829, 2022). "Functional studies of the variant in animal models have confirmed that the PIKFYVE gene might also be involved in the development of early onset cataracts in zebrafish." (PMID 37511188, 2023). "To investigate the possible roles of PIKFYVE in the development of cataracts, we first confirmed its expression in human anterior lens capsules by quantitative RT-PCR." (PMID 35023829, 2022). "In contrast to the healthy control, the PIKFYVE gene in the cataract patients carried a G to A heterozygous substitution in the 39th exon, which leads to the replacement of a highly conserved amino acid glycine (G) by glutamate (E) at position 1943 in the PIPK domain." (PMID 35023829, 2022).
Crohn disease (3 papers, 2021 to 2024). A gastrointestinal disorder characterized by chronic inflammation involving all layers of the intestinal wall, noncaseating granulomas affecting the intestinal wall and regional lymph nodes, and transmural fibrosis. "Although apilimod was ineffective in clinical trials against Crohn’s disease and rheumatoid arthritis, the search for new PIKFYVE inhibitors, such as AS2677131 and AS2795440, to treat autoimmune and inflammatory diseases continues." (PMID 38994949, 2024).
Lowe Syndrome (3 papers, 2015 to 2021). "Stc1: Stanniocalcin1; TGFb: TGF-b; AgII: Angiotensin II; LRP2: Megalin; OCRL1: Gene mutated in Lowe Syndrome; PIKfyve: FYVE finger-containing phosphoinositide kinase (functions along OCRL1); TGN: Trans Golgi Network; ER: Endoplasmic Reticulum." (PMID 35098216, 2021).
macular corneal dystrophies (3 papers, 2019 to 2023). "For example, direct correlations have been established between mutations in CHST6, UBIAD1, SLC4A11, PIKFYVE, TACSTD2, and DCN with macular corneal dystrophies (MCD), Schnyder CD, congenital hereditary endothelial dystrophy, fleck CD, gelatinous drop-like CD, and congenital stromal CD, respectively." (PMID 31555324, 2019).
prostate carcinoma (3 papers, 2016 to 2024). A carcinoma that arises from epithelial cells of the prostate gland. "An effective PIKFYVE degrader molecule was developed termed PIK5-12d that strongly bind and degrades PIKFYVE protein (DC50 = 1.5 nM) and outperformed both apilimod and YM201636 in suppressing prostate cancer cells growth both in vitro and in vivo." (PMID 38994949, 2024). "Importantly, the increased MHC-I surface expression by PIKfyve inhibition was also observed in various human cancer models, including MIA PaCa2, LNCaP, and prostate cancer patient–derived xenografts." (PMID 38011559, 2023).
rheumatoid arthritis (3 papers, 2021 to 2024). A chronic, systemic autoimmune disorder characterized by inflammation in the synovial membranes and articular surfaces. "Apilimod is a selective PIKfyve inhibitor, which abrogates the synthesis of IL-12 and IL-23 in patients with Crohn’s disease (CD), rheumatoid arthritis (RA), and psoriasis." (PMID 37359517, 2023).
congenital cataracts (2 papers, 2023 to 2024). "Mutations in key sites within the phosphatidylinositol phosphate kinase (PIPKc) domain of the PIKfyve gene have been implicated in familial benign corneal dystrophy and congenital cataracts, although their precise pathogenesis remains elusive." (PMID 38891085, 2024). "Moreover, recent studies have linked PIKfyve mutations to congenital cataracts in both humans and zebrafish." (PMID 38891085, 2024). "In the eye, disruption of PIKFyve causes congenital cataracts in humans and zebrafish." (PMID 37007713, 2023). "These discoveries offer new avenues for the development of novel treatment strategies for PIKfyve-dependent genetic diseases, including congenital cataracts and lysosomal storage disorders." (PMID 38891085, 2024).
Lysosomal Disorders (2 papers, 2024). "In this study, we present findings from PIKfyve-deficient zebrafish embryos, revealing enlarged macrophages with giant vacuoles reminiscent of lysosomal storage disorders." (PMID 38891085, 2024). "We wondered whether SNARE mislocalization could contribute to the fusion defect during PIKfyve inhibition, given that SNAREs are known to be sequestered on the lysosome membrane in lysosomal storage disorders that alter cholesterol metabolism." (PMID 39433126, 2024).
Obesity (2 papers, 2017 to 2022). Accumulation of substantial excess body fat. "Altogether, these results unravel a novel role for PIKfyve in obesity‐associated cardiomyopathy and provide a promising therapeutic strategy to combat cardiometabolic complications in obesity." (PMID 28396567, 2017). "In the present study, we unravel a critical role for the phosphoinositide kinase PIKfyve in the control of stress‐induced mitochondrial damage, ROS generation, apoptosis, and ventricular dysfunction in obesity‐induced phenotype." (PMID 28396567, 2017). "We provide evidence that chronic inhibition of PIKfyve by STA attenuates obesity‐related cardiometabolic phenotype by reducing mitochondrial oxidative stress and apoptosis through the deacetylase SIRT3." (PMID 28396567, 2017). "We provide evidence that PIKfyve inhibition reverses obesity‐induced cardiac mitochondrial damage and apoptosis by activating SIRT3." (PMID 28396567, 2017). "In HFD‐fed mice, PIKfyve inhibition prevented obesity‐induced impairments in cardiac function and structure." (PMID 28396567, 2017). "Here, we identify PIKfyve as a key regulator of cardiometabolic status and mitochondrial integrity in chronic diet‐induced obesity." (PMID 28396567, 2017). "In this study, we unravel a critical role of PIKfyve in the regulation of cardiometabolic status in obesity‐induced phenotype." (PMID 28396567, 2017). "Based on our in vitro data, we next asked whether PIKfyve inhibition was able to affect obesity‐induced oxidative stress and cardiac apoptosis." (PMID 28396567, 2017). "Considering the in vitro effects of STA on cellular responses to oxidative and metabolic stresses, we next examined whether PIKfyve inhibition could improve cardiometabolic phenotype in a mouse model of chronic high fat diet (HFD)‐induced obesity." (PMID 28396567, 2017). "Therefore, we hypothesized that MYH10, PAK4, and PIKfyve might be the targets of obesity-induced cognitive impairment, providing new ideas, and directions to understand the pathogenesis of obesity-induced cognitive impairment." (PMID 36408417, 2022).
osteosarcoma (2 papers, 2018 to 2021). A usually aggressive malignant bone-forming mesenchymal neoplasm, predominantly affecting adolescents and young adults. "All evidence from our study demonstrates that TRIM68, PIKFYVE, and DYNLL2 are high-risk genes involved in the development of osteosarcoma and can be used as biomarkers for predicting the prognosis of osteosarcoma." (PMID 33968741, 2021). "TRIM68, PIKFYVE, and DYNLL2 are high-risk genes involved in the development of osteosarcoma and can be used as possible biomarkers for predicting the prognosis of osteosarcoma." (PMID 33968741, 2021). "For example, PIKfyve promotes cell migration and invasion through activation of Rac1 in lung carcinoma, osteosarcoma or rhabdomyosarcoma cells, while inhibition of PIKfyve resulted in a significant decrease in cell migration velocity and persistence." (PMID 30445978, 2018). "The TRIM68, PIKFYVE, and DYNLL2 genes can be used as biomarkers for predicting the prognosis of osteosarcoma." (PMID 33968741, 2021). "The expressions of TRIM68, PIKFYVE, and DYNLL2 were higher in the osteosarcoma cells compared to the control cells." (PMID 33968741, 2021).